STAG3 (STAG3 cohesin complex component)
Description:
Meiosis specific component of cohesin complex. The cohesin complex is required for the cohesion of sister chromatids after DNA replication. The cohesin complex apparently forms a large proteinaceous ring within which sister chromatids can be trapped. At anaphase, the complex is cleaved and dissociates from chromatin, allowing sister chromatids to segregate. The meiosis-specific cohesin complex probably replaces mitosis specific cohesin complex when it dissociates from chromatin during prophase I.
Synonyms: SA3; SPGF61
Tractability: PROTAC: ubiquitination databases record sites on it.
Gene: Protein-coding gene on chromosome 7 (100,177,563 to 100,214,387, forward strand). Ensembl gene ENSG00000066923.
Subcellular location: Nucleus; Chromosome; Chromosome, centromere
Subcellular location (Human Protein Atlas): Nucleoli; Nucleoplasm
Pathways (Reactome):
Reproduction: Meiotic synapsis
Gene Ontology:
Molecular function: chromatin binding
Biological process: establishment of meiotic sister chromatid cohesion; synaptonemal complex assembly; meiotic cell cycle
Cellular component: extracellular region; meiotic cohesin complex; nucleolus; nucleoplasm; chromatin; nucleus; synaptonemal complex; chromosome; chromosome, centromeric region
Genetic constraint (gnomAD): Loss-of-function variants: 98 observed, 151.56 expected, observed/expected ratio (o/e) 0.65, 90% interval 0.55 to 0.76. The upper end of that interval is the gene's LOEUF score, 0.76, which puts it in group 3 of 6, group 1 being the genes least tolerant of losing a copy. Missense variants: 1,139 observed, 1,479.2 expected, observed/expected ratio (o/e) 0.77, 90% interval 0.73 to 0.81. Synonymous variants: 499 observed, 578.4 expected, observed/expected ratio (o/e) 0.86, 90% interval 0.8 to 0.93.
Homologues: Orthologues: chimpanzee STAG3 (99% identical), macaque STAG3 (96% identical), dog STAG3 (87% identical), pig STAG3 (83% identical), rabbit STAG3 (80% identical), guinea pig STAG3 (79% identical), rat Stag3 (79% identical), mouse Stag3 (78% identical), tropical clawed frog stag3 (45% identical), Caenorhabditis elegans scc-3 (28% identical), Drosophila melanogaster SA2 (19% identical), zebrafish stag3 (15% identical). Paralogues in human: STAG2 (50% identical), STAG1 (49% identical).
Diseases named in the same sentence as STAG3 in open-access papers:
STAG3 is named in the same sentence as 41 diseases in open-access papers, as found by Europe PMC text mining. Sharing a sentence is not in itself a finding about the gene and the disease. The quoted sentences say what the papers report.
Infertility (7 papers, 2014 to 2025). "Studies on the function of the STAG3 gene in mice have mainly focused on chromosomal abnormalities and infertility caused by homozygous mutation of STAG3." (PMID 35941537, 2022). "Studies on the abnormal expression or mutation of the STAG3 gene in humans have typically focused on follicular development, infertility, premature ovarian failure, spermatogenesis disorders and male infertility." (PMID 35941537, 2022). "Both Stag3-deficient male and female mice are infertile due to the early prophase I arrest and apoptosis in both male and female germ cells." (PMID 27906670, 2017). "MRPL50 could therefore be considered a candidate gene underlying male infertility, consistent with many known POI genes that can cause infertility of both sexes (e.g. STAG3, ZSWIM7, etc.)." (PMID 37148394, 2023). "Furthermore, it was recently shown that an inherited mutation in human Stag3 that gives rise to infertility and gonadal failure." (PMID 24992337, 2014). "Three studies report infertility in 3 males, all of whom were carriers of the pathogenic variants reported (PSMC3IP, NR5A1, and STAG3 variants)." (PMID 38737775, 2023). "Our findings imply that abnormalities in human STAG3 will give rise to chromosome defects, infertility and gonad atrophy." (PMID 24992337, 2014). "Knowledge of STAG3 is lacking, but some studies have shown that STAG3 is correlated with abnormalities, infertility and premature ovarian failure in women and have demonstrated the relationship between abnormal expression or mutation of STAG3 and male infertility and spermatogenesis disorders." (PMID 35941537, 2022). "The segregation of pathogenic loss of function variants in PSMC3IP, NR5A1, and STAG3 with POI in 13 female carriers and non-obstructive azoospermia (NOA) in three male carriers in the studied pedigrees suggested a significant role of these variants in infertility in both genders." (PMID 38737775, 2023).
male infertility (7 papers, 2022 to 2025). The inability of the male to effect fertilization of an ovum after a specified period of unprotected intercourse. "Previous studies have found that STAG3 gene mutations can cause male infertility due to meiotic arrest, and STAG3 knockout can cause azoospermia in male mice." (PMID 37180060, 2023). "The mutations of STAG3 cohesin cause male infertility via meiotic arrest." (PMID 39659446, 2024). "Similar to the variants in the STAG3 gene, biallelic variants in the SPIDR gene cause both female and male infertility." (PMID 41393291, 2025). "These abnormally expressed genes, such as Stra8, Stag3, Atr and Dazl, caused by SRSF2 deletion finally result in the failure of spermatogenesis and male infertility." (PMID 37867192, 2023). "The stromal antigen 3 (STAG3) gene, which encoding a meiosis-specific cohesin component, is a strong candidate for male infertility." (PMID 36060931, 2022).
premature ovarian failure (6 papers, 2015 to 2022). "Of note, STAG3 loss of function is associated with premature ovarian failure, and a common allele is associated with elevated risk of developing EOC." (PMID 34215221, 2021). "While variant in STAG3 was identified in premature ovarian failure and oocytes in Stag3–/– female mice were arrested at early prophase I, the knockout male mice were also infertile and showed meiotic arrest and azoospermia." (PMID 33980954, 2021). "A STAG3 frameshift mutation is apparently the cause of premature ovarian failure in humans." (PMID 25993311, 2015).
Azoospermia (5 papers, 2021 to 2025). Absence of any measurable level of sperm,whereby spermatozoa cannot be observed even after centrifugation of the semen pellet. "Variants in cohesin components, such as SMC1, or the existence of specific variants, like STAG3, have been associated with impaired homolog pairing, premature chromatid separation, and meiotic arrest, which can result in oligozoospermia or azoospermia." (PMID 41155851, 2025). "Furthermore, recent studies in humans have identified biallelic pathogenic variants in STAG3 in men with non-obstructive azoospermia, underscoring its clinical importance as a key factor in meiotic failure and infertility." (PMID 41155851, 2025). "Stag3–/– male mice showed no overt phenotype apart from sterility, which is due to azoospermia and meiotic arrest." (PMID 33980954, 2021).
colorectal cancer (5 papers, 2013 to 2023). A primary or metastatic malignant neoplasm that affects the colon or rectum. "That at least some of these genes are relevant to human cancer is supported by a recent report that high STAG3 expression in colorectal cancer is associated with metastasis, drug resistance, and poor clinical outcomes." (PMID 34236315, 2021). "Conversely, high STAG3 expression is associated with poor prognosis, metastasis, and disease recurrence in colorectal cancer patients." (PMID 34830845, 2021). "In colorectal cancer cell lines, STAG3 downregulation enhances sensitivity to chemotherapeutics and impairs DNA damage repair." (PMID 34830845, 2021). "The human genes SMC1, SMC3, NIPBL, STAG3, RNF20, FBXW7/CDC4, MRE11A, RAD54B and BLM have been found to be mutated in colorectal cancer, and together account for approximately 25% of the CIN mutational spectrum of this disease." (PMID 23382697, 2013). "Stromal antigen (STAG) 3 promotes colorectal cancer cell migration and chemoresistance suggesting that STAG3 may be a potential therapeutic target and prognostic biomarker for colorectal cancer." (PMID 37693042, 2023).
lymphoma (5 papers, 2006 to 2022). A malignant (clonal) proliferation of B- lymphocytes or T- lymphocytes which involves the lymph nodes, bone marrow and/or extranodal sites. "STAG3 is also associated with lymphoma, and colorectal and testicular cancers." (PMID 32631357, 2020).
melanoma (4 papers, 2021 to 2025). A malignant, usually aggressive tumor composed of atypical, neoplastic melanocytes. "In contrast, STAG2 or STAG3 mutation in melanoma conferred resistance to BRAF inhibition owing to reactivation of MEK-MAPK (ERK) signaling, which suggests that in a melanoma context, STAG2 mutation status could inform therapeutics." (PMID 34202641, 2021). "A previous study demonstrated that STAG3 may be a tumor suppressor gene, and that loss of STAG3 may cause drug resistance in melanoma." (PMID 33712015, 2021). "The loss of STAG3 has been associated with increased metastasis and drug resistance in melanoma." (PMID 34888264, 2021). "In a later work based on IHC of melanoma specimens, it was found that DUSP6 protein, as well as STAG2 and STAG3, two cohesin complex components, are decreased following treatment with BRAF or MEK (dabrafenib, trametinib, andvemurafenib) inhibitors." (PMID 40943262, 2025). "Consistently, melanoma cell lines (A375, Mel1617, WM902, WM983, and M14) resistant to BRAFi or MEKi showed reduced expression of STAG2 and STAG3, and their KD led to a further decrease of DUSP6 as well as of BRAFi sensitivity, along with an increase in ERK1/2 phosphorylation." (PMID 40943262, 2025).
female infertility (3 papers, 2019 to 2025). Diminished or absent ability of a female to achieve conception. "Both MCM8 and BRCA2 have been shown to be associated with meiosis and female infertility, and STAG3 is a meiosis-specific gene involved in female infertility." (PMID 31803224, 2019). "However, it remains enigmatic whether in-frame variants of STAG3 can cause POI and female infertility." (PMID 31803224, 2019).
ovarian carcinoma (3 papers, 2020 to 2022). A malignant neoplasm originating from the surface ovarian epithelium. "We predict that STAG3 plays a role in ovarian cancer tumorigenesis, based on its gene fusions and upregulated expression, as well as the central role in cancer of the mitotic cohesin proteins STAG1 and STAG2, whose mutation or inactivation cause aneuploidy." (PMID 34215221, 2021).
hepatocellular carcinoma (2 papers, 2022 to 2023). A malignant tumor that arises from hepatocytes. "Chromosome instability caused by STAG3 gene mutation may potentially promote tumor progression, but the effect of STAG3 on hepatocellular carcinoma (HCC) and the related molecular mechanism are not reported in the literature." (PMID 35941537, 2022).
lung carcinoma (2 papers, 2017 to 2021). "In order to study the importance of these genes in lung cancer cells, we performed siRNA knockdowns of STAG3 and PODXL2 in control and sgMGA cells." (PMID 34236315, 2021). "Importantly, we observed that four of the five genes (STAG3, PODXL2, NHLRC1, and ZCWPW1) identified from our analysis in lung cancer models were significantly upregulated upon loss of MGA." (PMID 34236315, 2021).
Primary amenorrhea (2 papers, 2021 to 2024). "This could be explained by the fact that pathogenic variants in these genes (for instance STAG3, MCM8 or PSMC3IP) result most often in severe changes in the maintenance of the ovarian reserve and cause a rapid loss of ovarian function, resulting in POI and primary amenorrhea." (PMID 39595984, 2024).
amenorrhea (1 paper, 2020). The absence of menses in a woman who has achieved reproductive age. "Two pathogenic heterozygous loss-of-function variants in STAG3 were identified in one woman presenting with primary amenorrhea using whole-exome sequencing." (PMID 33095795, 2020).
Cirrhosis (1 paper, 2022). A chronic disorder of the liver in which liver tissue becomes scarred and is partially replaced by regenerative nodules and fibrotic tissue resulting in loss of liver function. "We subsequently found that low STAG3 expression was correlated with cirrhosis, higher AFP levels, larger tumor size and lower pathological stage." (PMID 35941537, 2022).
Intellectual disability (1 paper, 2020). "Homozygous mutations in AP4M1, located in the region including PILRA and STAG3, cause spastic tetraplegia, intellectual disability, and white matter loss." (PMID 30108311, 2020).
leukemia (1 paper, 2022). A malignant (clonal) hematologic disorder, involving hematopoietic stem cells and characterized by the presence of primitive or atypical myeloid or lymphoid cells in the bone marrow and the blood. "Additionally, to test whether ESC differentiation changes the expression kinetics of REC8 and STAG3, we differentiated ESCs by withdrawing leukemia inhibitory factor from the culture medium." (PMID 35241136, 2022).
lung adenocarcinoma (1 paper, 2021). A carcinoma that arises from the lung and is characterized by the presence of malignant glandular epithelial cells. "(D, E) Log ratios of (D) PODXL2 and (E) STAG3 expression in MGA altered vs. WT lung adenocarcinoma patients." (PMID 34236315, 2021).
metastatic melanoma (1 paper, 2021). A melanoma that has spread from its primary site to another anatomic site. "Mutant STAG3 has also been implicated in metastatic melanoma, where it plays a role in reactivating MAPK signaling after treatment with a targeted kinase inhibitor." (PMID 34215221, 2021).
Miscarriage (1 paper, 2017). A pregnancy that ends at a stage in which the fetus is incapable of surviving on its own, defined as the spontaneous loss of a fetus before the 22th week of pregnancy. "As a result, our data also reveal that loss of Stag3 produces a higher incidence of aneuploid eggs which are highly correlated with miscarriage, birth defects and genetic disorders." (PMID 27906670, 2017).
Obstructive azoospermia (1 paper, 2021). Absence of any measurable level of sperm in his semen, resulting from post-testicular obstruction or retrograde ejaculation. "Whether variants of the STAG3 gene exist in Chinese idiopathic non-obstructive azoospermia (NOA) patients needs to be determined." (PMID 33980954, 2021).
oligoasthenoteratozoospermia (1 paper, 2025). A form of male infertility that is characterized by a combination of low number or oligozoospermia, poor motility or asthenozoospermia, and abnormal shape or teratozoospermia of sperms. "In the family of patient P26, who carried compound-heterozygous variants in the STAG3 gene, segregation studies led to the identification of an affected brother with severe oligoasthenoteratozoospermia." (PMID 41393291, 2025).
Sézary Syndrome (1 paper, 2019). "Our results show significant differential gene expression of STAG3, SGO2, SYCP3, and DMC1 in a cohort of Sézary Syndrome patients when compared to healthy controls." (PMID 31214493, 2019).
Turner syndrome (1 paper, 2017). Turner syndrome is a chromosomal disorder associated with the complete or partial absence of an X chromosome. "When this is the case, the underlying pathogenetic mechanism of follicle depletion are heterogeneous ranging from genetic (Turner’s syndrome, mutations in the genes FMR-1, BMP-15, Foxl2, and recently identified MCM9, SYCE1, STAG3) to auto-immune and iatrogenic causes." (PMID 29176793, 2017).
tumor (14 papers, 2014 to 2024). "In HCC, low expression of STAG3 was associated with increased tumor size and poor prognosis." (PMID 35941537, 2022). "When dysregulated, the STAG3 gene can block sister chromatid aggregation, and this blockage can facilitate the aggregation of sister chromatids, block the mutation of the STAG3 gene and cause chromosomal instability, which may potentially promote tumor progression." (PMID 35941537, 2022). "The outcomes revealed that the mRNA expression level of STAG3 in the Tumor group was much greater than it was in the Normal group." (PMID 37828232, 2023). "STAG3, a component of the meiosis specific cohesin complex was expressed at a low level in B-cells, RT-qPCR of whole tumor tissue confirmed its differential expression between HPV(+) and HPV(−) tumors." (PMID 27462861, 2016). "Finally, the biological function of STAG3 in vivo was investigated through a xenotransplantation mouse tumor model." (PMID 37828232, 2023). "Finally, subcutaneous tumor experiments conducted in nude mice also confirmed that METTL3 regulated CRC progression through STAG3 in vivo." (PMID 37828232, 2023). "In contrast, the expression of genes, including STAG3, GATA5, and CACNB2, which are associated with cell proliferation or tumorigenesis, and PRAP1, which is primarily involved in the inhibition of tumor cell apoptosis, increased in mouse KrasG12D/Galc KO pancreatic organoids." (PMID 37848935, 2023). "This suggested that STAG3 might exhibit heterogeneity and undergo complex transcriptional regulation in different tumor types." (PMID 37828232, 2023). "STAG3 is a tumor-suppressor gene that may serve as a potential target for molecular therapy, which provides a new idea for the treatment of HCC." (PMID 35941537, 2022). "Moreover, the TUNEL staining results suggested that STAG3 overexpression promoted apoptosis in xenograft tumor tissue, and the results demonstrated that STAG3 effectively regulated tumor formation." (PMID 35941537, 2022). "In addition to this, RT-qPCR of CD200 and STAG3 was carried out on the whole tumor RNA samples used for the RNA-Seq (n=8 HPV(+) and n=8 HPV(−)." (PMID 27462861, 2016). "To explore the role of STAG3 in HCC, we found that the STAG3 protein level was significantly correlated with the T stage, pathological stage and tumor status in the TCGA dataset." (PMID 35941537, 2022). "STAG3 also inhibited the migration and invasion ability of HCC cells and was found to play a tumor suppressive role in HCC." (PMID 35941537, 2022). "Gene set enrichment analysis showed the role of AREG, STAG3 and CAV1 in dysregulated pathways of tumor." (PMID 33712015, 2021). "Gene set enrichment analysis (GSEA) showed the role of AREG, STAG3 and CAV1 in dysregulated pathways of tumor." (PMID 33712015, 2021). "A B-cell associated signature distinguished HPV(+) from HPV(−) tumors, and included the DEGs CD200, GGA2, ADAM28, STAG3, SPIB, VCAM1, BCL2 and ICOSLG; the immune signal relative to T-cells was qualitatively similar between TILs of both tumor cohorts." (PMID 27462861, 2016). "Moreover, cytofunctional tests revealed that the lentivirus-mediated overexpression of STAG3 in HCC cells inhibited cell proliferation, migration, and invasion; promoted apoptosis; induced G1/S phase arrest in vitro; and inhibited tumor growth in vivo." (PMID 35941537, 2022). "Although our data is suggestive of a broad tumor suppressive role of MGA and PRC1.6 via antagonizing transcription of MYC and E2F targets, further studies will be required to elucidate the functional relevance of individual MGA-PRC1.6 targets such as STAG3 in tumorigenesis." (PMID 34236315, 2021).
tumor (continued). "Considering that some CT antigens upregulated in HPV-positive cancers may promote genomic instability and that high expression of SYCP2 or STAG3 correlates with improved survival in HSNCC, it is conceivable that aberrant CT antigen expression may contribute to tumor chemo- and radiosensitivity." (PMID 34830845, 2021).